SPRY4 (sprouty RTK signaling antagonist 4)
Diseases named in the same sentence as SPRY4 in open-access papers (continued):
Sharing a sentence is not in itself a finding about the gene and the disease.
cancer (29 papers, 2011 to 2026). A tumor composed of atypical neoplastic, often pleomorphic cells that invade other tissues. "Specifically, we identify putative miRNA target sites in the 3′UTRs of BMPR1B, KLK3, and SPRY4 that are disrupted by both somatic and germline mutations and, also, are in linkage disequilibrium blocks with high scoring markers from cancer association studies." (PMID 23091610, 2012). "In addition, the promoter of SPRY4 remains susceptible to aberrant DNA methylation in some cancer types." (PMID 36384366, 2023). "Focusing on the mRNA expression in the stromal fibroblasts, we found that Spry2 and Spry4 are both greatly downregulated, but curiously, Spry1 is upregulated in the cancer fibroblasts." (PMID 38600092, 2024). "For instance, miR-411-5p, miR-1908, and miR-181 microRNAs downregulate SPRY4 by directly targeting and degrading SPRY4 transcripts in an assortment of cancer cells." (PMID 36384366, 2023). "The results are in accordance with the invasion data, showing that under SPRY4 inhibition, macrophages promote an increase in cancer cell protrusions, suggesting higher cancer cell motility, which is essential for a successful invasion." (PMID 37686663, 2023). "SPRY4 silencing promoted cancer cell invasion, reverting the reduced invasion of C3948 caused by macrophages." (PMID 37686663, 2023). "In summary, the studies showcase the various biological mechanisms by which SPRY4 is dysregulated in cancer." (PMID 36384366, 2023). "Among 97 pairs of tissues, SPRY4 was downregulated significantly, as compared to that of corresponding para-carcinoma tissues." (PMID 35484993, 2022). "Several reports showing concordant inhibition of cell proliferation and migration like in breast and brain cancer-derived cells demonstrate that in the same cell lines Spry4 is able to interfere with this pathway." (PMID 33670044, 2021). "As a negative regulator of signal transduction Spry4 protein is able to exert a tumor-suppressive role as observed for cancer derived from lung, breast tissue cells, or brain glia." (PMID 33670044, 2021). "The translation and transcription levels of SPRY4 genes between normal cell line and cancer cell lines were statistically different." (PMID 33879635, 2021). "The SPRY4 overexpression treatment resulted in the least amount of cancer cells in the lower chamber." (PMID 33879635, 2021). "SPRY4 intronic transcript 1 (SPRY4-IT1) derives from the intron two of the SPRY4 gene and has shown to act as an oncogenic factor or a tumor suppressor in different cancer types." (PMID 32154165, 2020). "SPRY4 intronic transcript 1 (SPRY4-IT1), an lncRNA derived from an intron within SPRY4 gene, has been recently revealed as oncogenic regulatory hubs or tumor suppressors in different cancers." (PMID 31092700, 2019). "Spry proteins are frequently down-regulated in cancers; however, the mechanism of Spry4 down-regulation remains incompletely understood." (PMID 28275056, 2017). "So WK found that knocking down SPRY4 inhibited AREG-induced cancer cell invasion and migration." (PMID 38686189, 2024). "Therefore, we mined the database and confirmed that expression of both Spry2 and Spry4 is downregulated, while Spry1 is upregulated in the cancer fibroblasts of the 4T1 model, similar to that in the human cancer." (PMID 38600092, 2024). "Furthermore, several TFs have been reported to directly bind to the promoter region and regulate SPRY4 in a variety of cancer cells." (PMID 36384366, 2023). "In addition, ZFX preferably binds promoters of oncogenes containing CpG islands like SPRY4 and is considered a transcriptional activator in many cancer cells." (PMID 36384366, 2023). "Altogether, in contrast to other cancers, SPRY4 is epigenetically upregulated and may therefore serve a different function in CRC, which is yet to be discovered." (PMID 36384366, 2023).
cancer (continued). "When SPRY4 was inhibited, in the presence of macrophages, it also significantly promoted the invasion of both cancer cells, with C3948 restoring the invasion ability of siNT monoculture (p < 0.05), but at increased levels, and T235 exhibiting the highest level of invasion of all tested conditions." (PMID 37686663, 2023). "SPRY4 is also epigenetically dysregulated in cancer cells by several biological mechanisms." (PMID 36384366, 2023). "In cancer and other human diseases, SPRY4 is dysregulated by several various biological mechanisms." (PMID 36384366, 2023). "Additionally, the study pinpoints a Spry4 variation expanding the applicability of Spry4 in a potential cancer therapy." (PMID 33670044, 2021). "Additionally, our results can be important knowledge to increase the feasibility of Spry4 in targeted therapy of cancer." (PMID 33670044, 2021). "In addition, SPRY4 also exerts regulatory effects on cell growth, differentiation, and metastasis during the development of malignant tumors in various types of cancers." (PMID 33879635, 2021). "Further study is warranted to evaluate whether this function of Spry4 is broadly conserved in multiple cancer types and stages of progression." (PMID 26973433, 2016). "SPRY proteins, including SPRY4, have been shown to inhibit cancer cell migration." (PMID 26392417, 2015). "SPRY4 is involved in the KITLG-KIT pathway, which has been associated with cancer." (PMID 23091610, 2012). "Moreover, SPRY4 manifests its potential as a prognostic biomarker in specific cancers." (PMID 38686189, 2024). "The lncRNAs SPRY4 intronic transcript (SPRY4-IT1) by controlling the expression of HIF-1α, which is abundantly expressed in breast cancer tissues, can encourage cancer cell metastasis." (PMID 41614928, 2026). "Knockdown of SPRY4 accelerates the occurrence and progression of AML, mainly by increasing RAS signaling to promote cancer development." (PMID 38686189, 2024). "For ERRFI1, RTN4, PHF7, SPRY4, CCND2, and RPL19, H3K36me3 and H3K79me2 enriched higher signals in normal cell lines than that in cancer cells, and the signals of H3K79me2 changed more significantly than H3K36me3 during tumorigenesis." (PMID 37426199, 2023). "While Spry3 expression was on average elevated in cell lines originated from higher malignant tumors, Spry4 tended to be repressed in GBM and GS compared to cells derived from lower graded cancers." (PMID 31374860, 2019). "SPRY4, as a negative regulator of the RAS pathway, plays a role in inhibiting cancer development." (PMID 38686189, 2024). "SPRY4 protein assumes a pivotal role in the regulation of the RTK pathway, governing crucial aspects of organogenesis, developmental processes, and the emergence of malignant neoplasms." (PMID 38686189, 2024). "SPRY4 was also suggested to be a downstream target of the non-canonical WNT (Wingless-related integration site) signaling pathway, inhibiting cancer cell growth, migration, and invasion in non-small-cell lung cancer (NSCLC)." (PMID 37686663, 2023).
infection (6 papers, 2013 to 2025). The state of being infected such as from the introduction of a foreign agent such as serum, vaccine, antigenic substance or organism. "In AIS MSCs, SPRY4 was remarkably upregulated following lenti-SPRY4 infection, confirmed by qRT-PCR and western blot assay." (PMID 31645544, 2019). "Furthermore, oil red O staining and quantification showed that more lipid droplets formed after lenti-SPRY4 infection, suggesting that there were more adipocytes and that hAMSC adipogenesis had been promoted." (PMID 36082406, 2022). "Additionally, we observed that infection of the cells with the same amount of adenoviruses expressing Spry4Y241 or the Spry4 wildtype protein resulted in a comparable yield of Spry4 protein levels." (PMID 33670044, 2021). "The top upregulated genes in KSHV lytic and mixed infection spots are predicted to encode proteins that regulate angiogenesis including ADAMTS9, KDR and PGF, endothelial cell development including KDR and STC1, and cell-substrate adhesion, SPRY4, ITGA1, ADAMTS9, KDR, MMP12." (PMID 39386738, 2024). "The number of regulated genes declined at 48 h post infection to 5.4% and increased again in the chronically infected cells to constitute 10.1% of the genes in this category, with a modified spectrum of highly induced genes, namely IL3RA, IL6, IL24 and SPRY4." (PMID 23326599, 2013).
adenocarcinoma (1 paper, 2023). A common cancer characterized by the presence of malignant glandular cells. "Increased copy number of SPRY4 may contribute to the increased expression observed in this study, and was therefore investigated in CRC patient adenocarcinomas classified as SPRY4-diploid compared against patients with copy number gains of SPRY4." (PMID 36384366, 2023). "Utilizing CRC patients in TCGA data repository, we found no group differences in SPRY4 transcript expression between patient adenocarcinomas identified as SPRY4-diploid or patients with copy number gains of SPRY4." (PMID 36384366, 2023).
SPRY4 also shares sentences with these, for which no sentence is quoted: esophageal squamous cell carcinoma (3 papers); adolescent idiopathic scoliosis (1); Anaplastic Thyroid Cancer (1); Anxiety (1); astrocytomas (1); breast tumor (1); colitis (1); congenital hypogonadotropic hypogonadism (1); cryptorchidism (1); Fuhrmann syndrome (1); gastric adenocarcinoma (1); gastrointestinal tumors (1); germ cell tumor (1); hemolytic-uremic syndrome (1); invasive ductal carcinoma (1); liver cancer (1); lung adenocarcinoma (1); multiple myeloma (1); myocardial infarction (1); Noonan syndrome (1); of puberty (1); papillary thyroid carcinomas (1); Phocomelia (1); psychiatric disorder (1); Sagittal craniosynostosis (1); teratoma (1); testicular germ cell tumours (1); yolk sac tumour (1).